KRT31 (keratin 31)
Synonyms: HHA1; KRTHA1; Ha-1; HA1
Tractability: No criterion of Open Targets' tractability assessment is met for any kind of drug.
Gene: Protein-coding gene on chromosome 17 (41,393,721 to 41,397,608, reverse strand). Ensembl gene ENSG00000094796.
Subcellular location (Human Protein Atlas): Cytosol; End piece; Principal piece; Equatorial segment; Mid piece
Pathways (Reactome):
Developmental Biology: Formation of the cornified envelope; Keratinization
Gene Ontology:
Molecular function: protein binding; structural constituent of cytoskeleton; structural constituent of skin epidermis; structural molecule activity
Biological process: epidermis development; epithelial cell differentiation; intermediate filament organization; morphogenesis of an epithelium
Cellular component: extracellular exosome; extracellular region; cytoskeleton; cytosol; intermediate filament; keratin filament
Genetic constraint (gnomAD): Loss-of-function variants: 28 observed, 43.67 expected, observed/expected ratio (o/e) 0.64, 90% interval 0.47 to 0.88. The upper end of that interval is the gene's LOEUF score, 0.88, which puts it in group 3 of 6, group 1 being the genes least tolerant of losing a copy. Missense variants: 510 observed, 559.15 expected, observed/expected ratio (o/e) 0.91, 90% interval 0.85 to 0.98. Synonymous variants: 231 observed, 238.64 expected, observed/expected ratio (o/e) 0.97, 90% interval 0.87 to 1.08.
Homologues: Orthologues: chimpanzee KRT31 (99% identical), macaque KRT31 (99% identical). Paralogues in human: KRT33B (91% identical), KRT33A (91% identical), KRT34 (85% identical), KRT36 (69% identical), KRT35 (69% identical), KRT32 (67% identical), KRT38 (60% identical), KRT40 (59% identical), KRT39 (59% identical), KRT37 (58% identical), KRT14 (49% identical), KRT16 (49% identical), and 56 more.
Diseases named in the same sentence as KRT31 in open-access papers:
KRT31 is named in the same sentence as 9 diseases in open-access papers, as found by Europe PMC text mining. Sharing a sentence is not in itself a finding about the gene and the disease. The quoted sentences say what the papers report.
dysplasia (1 paper, 2020). A usually neoplastic transformation of the cell, associated with altered architectural tissue patterns. "Based on global transcriptomics by RNA sequencing, OLK with dysplasia is different from OLK without dysplasia in terms of its molecular pathology: at least 47 genes were found to be differentially expressed between OLK with and without dysplasia, including SAA1, SAA2, and KRT31." (PMID 33327496, 2020).
monilethrix (1 paper, 2022). Monilethrix is a rare genodermatosis characterized by a hair shaft dysplasia resulting in hypotrichosis. "Interestingly, mutations in type II hard and soft hair keratins (KRT75, KRT81,83,85,86), but not type I hair keratins (KRT25-28, KRT31-40), have reported associations with other genetic hair disorders such as Monilethrix, pseudofolliculitis barbae, and hair ectodermal dysplasia." (PMID 35145093, 2022).
psoriasis (1 paper, 2022). An autoimmune condition characterized by red, well-delineated plaques with silvery scales that are usually on the extensor surfaces and scalp. "KRT15, KRT24, KRT31, KRT37, KRT78 are differentially expressed in psoriasis, while KRT5 and KRT14 are specific for AD." (PMID 35874668, 2022).
tumor (2 papers, 2008 to 2015). "Keratin-31, vimentin, prohibitin, etc., were up-regulated in tumour stroma; Rho GDP dissociation inhibitor (GDI) β, superoxide dismutase, keratin-19, and annexin-A2 were down-regulated in tumour stroma." (PMID 26184160, 2015). "Consistent with our statistical analysis, quantitative PCR confirmed the upregulation of BST2 and MFAP2 and the downregulation of KRT31 when samples of HNSCC were compared to tumor-free surgical margins." (PMID 19014460, 2008).
KRT31 also shares sentences with these, for which no sentence is quoted: alopecia areata (1 paper); colorectal adenoma (1); infection (1); lymphoma (1); Pseudofolliculitis barbae (1).